FTO (FTO alpha-ketoglutarate dependent dioxygenase)
Diseases named in the same sentence as FTO in open-access papers (continued):
Sharing a sentence is not in itself a finding about the gene and the disease.
Sleep apnea (2 papers, 2014 to 2025). An intermittent cessation of airflow at the mouth and nose during sleep is known as sleep apnea. "The meta-analysis also demonstrated that FTO variant rs8050136 was significantly associated with sleep apnea (OR = 1.14, 95% CI = 1.07–1.22, p = 3.33 × 10−5); however, the association was attenuated after adjustment for body mass index (BMI)." (PMID 25177340, 2014).
uterine cancer (2 papers, 2023 to 2025). Primary or metastatic malignant neoplasm involving the uterine corpus and/or the cervix. "Targeted inhibition of RNA m6A demethylase FTO may impart beneficial effects in uLMS and provide a promising and novel strategy for treating patients with this aggressive uterine cancer." (PMID 37175660, 2023).
uveitis (2 papers, 2024 to 2025). An inflammatory process affecting a part of or the entire uvea. "In contrast to a hypothetical pro-inflammatory role, accumulating evidence indicates that FTO is downregulated in microglia during uveitis." (PMID 41315216, 2025). "Single-cell sequencing (scRNA-seq) and validation studies showed significantly reduced FTO expression in retinal microglia from uveitis mice and in microglia clone 3 (HMC3) cells from inflammatory patients." (PMID 39686999, 2024). "Decreased FTO may promote microglial inflammation in autoimmune uveitis (EAU), suggesting that restoring or activating FTO function could serve as a potential therapeutic strategy for uveitis." (PMID 41315216, 2025).
Wilms tumor (2 papers, 2024 to 2025). An embryonal neoplasm characterized by the presence of epithelial, mesenchymal, and blastema components. "Notably, certain single nucleotide polymorphisms (SNPs) that are present in m1A writers (TRMT6), erasers (FTO), and readers (YTHDC1 and YTHDF2) have been associated with the risk of Wilms tumour risk, emphasising the significant role of m1A modification regulators in Wilms tumour development." (PMID 41017026, 2025).
acanthosis nigricans (1 paper, 2020). A melanotic cutaneous lesion that develops in the axilla and other body folds. "This study aimed to determine the association between FTO (rs9939609) polymorphism with clinical (BMI, acanthosis nigricans, hirsutism) and biochemical (serum kisspeptin and testosterone levels) characteristics of PCOS in a cohort of Sri Lankan women." (PMID 32050935, 2020). "Interestingly, we observed that the majority of subjects with PCOS had acanthosis nigricans (a clinical marker associated with IR - thickened, velvety, relatively darker areas of skin on the neck, armpit and in skin folds) and had the A allele (either AT or AA) in the FTO rs9939609 polymorphism." (PMID 32050935, 2020).
adenomyosis (1 paper, 2020). The growth of endometrial tissue inside the muscular wall of the uterine corpus. "From the analysis of the gene expression profile of GSE78851, we found that METTL3, ZC3H13, FTO, and YTHDC1 were all significantly decreased in the eutopic endometrium of adenomyosis patients versus controls." (PMID 32719721, 2020).
alcohol addiction (1 paper, 2014). "In conclusion, our study proves that there is an inverse association between rs9939609 polymorphism in FTO gene and completed suicide which is independent from association between FTO and alcohol addiction." (PMID 25265168, 2014). "No confounding effect of alcohol addiction in our study is supported by the lack of difference in FTO allele/genotype distribution between cases who were under influence of ethanol at the time of death and those who were not." (PMID 25265168, 2014).
Arrhythmia (1 paper, 2014). Any cardiac rhythm other than the normal sinus rhythm. "Taken together these findings point to a close link between FTO deficiency and arrhythmia vulnerability, particularly in conditions of sustained stress exposure (restraint stress)." (PMID 24743632, 2014). "It is interesting that arrhythmia vulnerability in FTO deficient mice was (i) induced by stress exposure, as arrhythmic events were only sporadically noted during baseline recordings, and (ii) clearly more pronounced in response to the restraint than the injection stress." (PMID 24743632, 2014). "We also evaluated whether supposed cardiac sympathetic hyperactivity in FTO knockout mice was associated with increased arrhythmia vulnerability, and investigated potential mediating mechanisms at the electrical and structural level of the heart." (PMID 24743632, 2014).
Autoimmunity (1 paper, 2022). The occurrence of an immune reaction against the organism's own cells or tissues. "m6A elements (FTO, YTHDF2, YTHDF3, or YTHDC2) might target ISG15, stimulate the expression of ISG15, and activate the type I IFN signaling pathway, playing an active role in initiating the autoimmunity in pSS." (PMID 36465909, 2022).
B-cell acute lymphoblastic leukemia (1 paper, 2025). A neoplasm of lymphoblasts committed to the B-cell lineage, typically composed of small to medium-sized blast cells. "Similarly, a previous study also showed that in B-cell acute lymphoblastic leukemia cells, FTO inhibition caused nucleolar stress by suppressing pre-rRNA levels." (PMID 41301545, 2025).
behavioural problems (1 paper, 2012). "Associations of child FTO at rs9939609 with behavioural problems at 3 years (n = 1718)." (PMID 23155456, 2012).
benign ovarian tumour (1 paper, 2022). "To compare the expression differences of FTO in various tissues, we used 5 normal ovarian tissues, 5 benign ovarian tumour tissues, 5 borderline ovarian tumour tissues, and 54 EOC tissues to test the expression of FTO by IHC." (PMID 36358640, 2022).
bone metastasis (1 paper, 2024). Transfer of a neoplasm from its primary site to bones. "Decreased FTO expression was an independent indicator of worse survival, and the level of DDIT4 was considerably elevated in patients with bone metastasis." (PMID 38384328, 2024).
brain injury (1 paper, 2025). Acute and chronic (see also brain INJURIES, CHRONIC) injuries to the brain, including the cerebral hemispheres, CEREBELLUM, and brain STEM. "In traumatic brain injury models, FTO downregulation correlates with elevated pro‐inflammatory cytokine secretion, suggesting a potential protective role for FTO against excessive neuroinflammation in PNDs contexts." (PMID 41018232, 2025).
cervical squamous intraepithelial lesions (1 paper, 2023). "However, one study reported a greater expression of mRNA expression of FTO in high-grade cervical squamous intraepithelial lesions than in normal tissues." (PMID 36582218, 2023).
childhood cancer (1 paper, 2018). "The study objective was to assess the prevalence of cardiovascular disease risk factors in patients treated for childhood cancer (N = 101) and to determine the involvement of clinical (cancer type and therapy) and/or genetic (FTO gene rs9939609 polymorphism) factors." (PMID 29675043, 2018).
chronic endometritis (1 paper, 2020). A non-granulomatous or granulomatous chronic inflammation of the endometrium. "Among the obtained models of gene–environment interactions, the most optimal for prediction was rs12324955 FTO × rs11031010 FSHB × chronic endometritis × aborts (OR = 3.90, Test." (PMID 33552117, 2020).
chronic hepatitis (1 paper, 2022). An active inflammatory process affecting the liver for more than six months. "Furthermore, in both murine chronic hepatitis models induced by HFD or chemicals, we demonstrated that overexpression of FTO facilitates the liver injury and inflammation via induction of IL-17RA." (PMID 36172147, 2022).
chronic myeloid leukaemia (1 paper, 2025). "In this study, we demonstrate that homoharringtonine (HHT), an FDA-approved therapeutic agent for chronic myeloid leukaemia (CML), inhibits this immune evasion by targeting the FTO/m6A/LILRB4 signalling pathway in monocytic AML." (PMID 40590394, 2025).
colorectal adenocarcinoma (1 paper, 2023). The most common type of colorectal carcinoma. "FTO is also found markedly upregulated in colorectal adenocarcinoma tissues." (PMID 36874096, 2023).
conjunctival melanoma (1 paper, 2025). "This FTO-driven activation of proangiogenic CAFs significantly promotes tumor progression by fueling angiogenesis in conjunctival melanoma, thereby establishing FTO as a therapeutic target with translational potential for antiangiogenic strategies in oncology." (PMID 40986143, 2025). "Furthermore, the m6A demethylase FTO is specifically upregulated in CAFs of conjunctival melanoma, where it removes m6A modifications from VEGFA and EGR1 mRNAs, thereby blocking YTHDF2-mediated mRNA decay and enhancing their stability and expression." (PMID 40986143, 2025).
Delayed puberty (1 paper, 2020). Passing the age when puberty normally occurs with no physical or hormonal signs of the onset of puberty. "However, recently, next-generation sequencing analysis has led to the discovery of new genes (i.e., IGSF10, HS6ST1, FTO, and EAP1) that are implicated in determining isolated self-limited delayed puberty in some families." (PMID 32508745, 2020).
dengue (1 paper, 2025). "Conversely, FTO inhibitors (e.g., FB23-2) enhance viral RNA sensing by stabilizing m6A-modified immunostimulatory RNAs, as shown in dengue and hepatitis C virus models." (PMID 40121516, 2025).
dry eye (1 paper, 2025). "Of note, a negative correlation was observed between FTO and miR‐31‐5p levels (r = −0.7924, p = 0.019) in SS dry eye patients." (PMID 40068094, 2025).
dyslipidaemia (1 paper, 2021). "Odds ratio analysis of FTO rs9939609, MC4R rs17782313, ACE I/D rs4646994 and MTHFR C677T rs1801133 polymorphisms with somatometric and dyslipidaemia variables among the Liangmai and Mizo tribes of Manipur." (PMID 34414818, 2021). "Genetic interaction results between FTO rs9939609, MC4R rs17782313, ACE I/D rs4646994 and MTHFR C677T rs1801133 for somatometric and dyslipidaemia variables using generalized multifactor dimensionality reduction (GMDR)." (PMID 34414818, 2021).
endometrial adenocarcinoma (1 paper, 2021). "Then, we used IPA to predict the possible target genes and network through which FTO led to the progression of endometrial adenocarcinoma." (PMID 34149936, 2021). "In our results, IGF1 and IRS1, essential factors in the glucose metabolism, thermogenesis, and glucose catabolic process 30, were considered as the potential target genes of FTO in the regulation of endometrial adenocarcinoma." (PMID 34149936, 2021). "IGF1 was also shown to mediate the functional role of FTO in endometrial adenocarcinoma." (PMID 34149936, 2021). "In conclusion, m6A methylation regulators, especially FTO, RBM15, and YTHDF1, are critical in the progression and prognosis of endometrial adenocarcinoma." (PMID 34149936, 2021). "GEO dataset also verified the differential expression of FTO and RBM15 between patients with endometrial adenocarcinoma and hyperplasia." (PMID 34149936, 2021). "In the present research, we elucidated that m6A RNA methylation regulators, especially FTO, RBM15, and YTHDF1, were likewise closely related with prognosis of endometrial adenocarcinoma." (PMID 34149936, 2021). "The decreased FTO expression and increased RBM15 expression in endometrial adenocarcinoma from our validation cohort was consistent with in silico analysis using TCGA and GEO datasets." (PMID 34149936, 2021). "Finally, we validated the mRNA expression of METTL3, FTO, RBM15, and YTHDF1 in clinical samples of endometrial tissues from endometrial adenocarcinoma patients and controls." (PMID 34149936, 2021). "We found that METTL3 and FTO mRNA expression was evidently decreased in endometrial adenocarcinoma while RBM15 mRNA expression was increased with no changes in YTHDF1 expression in cases versus controls." (PMID 34149936, 2021). "Furthermore, aberrant expression of erasers was also detected, and both FTO and ALKBH5 were significantly decreased in women with endometrial adenocarcinoma versus controls." (PMID 34149936, 2021). "From TCGA and GEO datasets, we found that FTO and RBM15 might take critical roles in the prognosis of endometrial adenocarcinoma." (PMID 34149936, 2021). "Hence, our results provided a potential mechanism and network for the regulation of FTO and RBM15 to the progression of endometrial adenocarcinoma." (PMID 34149936, 2021). "Moreover, we also validated the roles of FTO and RBM15 in the prognosis of endometrial adenocarcinoma using the GEO dataset and predicted the possible target genes and biological processes of FTO and RBM15, which might contribute to the regulation of these two genes to endometrial adenocarcinoma." (PMID 34149936, 2021). "Hence, FTO, RBM15, and YTHDF1 may regulate the RNA processing and translation of target genes involved in the cell cycle, thermogenesis and other pathways, leading to the tumor process and prognosis of endometrial adenocarcinoma." (PMID 34149936, 2021).
endothelial dysfunction (1 paper, 2023). In vascular diseases, endothelial dysfunction is a systemic pathological state of the endothelium (the inner lining of blood vessels) and can be broadly defined as an imbalance between vasodilating and vasoconstricting substances produced by (or acting on) the endothelium. "Moreover, rescue experiments suggested that other downstream genes regulated by FTO in endothelial dysfunction exist; however, the pathway that plays the dominant role remains unclear." (PMID 37781923, 2023).
Fanconi anemia (1 paper, 2022). Fanconi anemia (FA) is a hereditary DNA repair disorder characterized by progressive pancytopenia with bone marrow failure, variable congenital malformations and predisposition to develop hematological or solid tumors. "The data showed that FTO expression was negatively correlated with the protein level of PD-L1 in immune cells, was positively correlated with the EMT signaling pathway, and negatively correlated with DDR, cell cycle, nucleoside exercise repair, Fanconi anemia pathway, and other signaling pathways." (PMID 35311150, 2022).
fatty acid metabolism disorder (1 paper, 2021). "The complex role of FTO in different cardiovascular diseases indicates that it has an essential role in fatty acid metabolism disorder-induced heart injury, as well as provides an effective therapeutic strategy for the utilization of FTO inhibitors in metabolic diseases." (PMID 34881240, 2021).
gallstones (1 paper, 2022). Solid crystalline precipitates in the biliary tract, usually formed in the gallbladder, resulting in the condition of cholelithiasis. "These loci are located in seven different genes, including SLC4A5, MUC4, FTO, NPC1 and FXYD2 genes that may increase the risk of gallstone in the Tibetan population, while CFTR and ADCY2 genes that reduce the risk of gallstone in the Tibetan population." (PMID 35651949, 2022). "In humans, the overexpression of FTO gene is manifested in the increase of body mass index (BMI) and basal metabolic rate (BMR) found that people with elevated BMI are more likely to suffer from symptomatic gallstone disease by comparing gallstone people with healthy people." (PMID 35651949, 2022).
HCMV infection (1 paper, 2022). "Our experiments saw consistent results in vascular endothelial cells, with a slight difference that we did not see an increase in the demethylases ALKBH5 and FTO after HCMV infection." (PMID 35359726, 2022). "Although our previous results showed that the expression of ALKBH5 and FTO did not change after HCMV infection, we still wondered whether ALKBH5 or FTO was involved in the HCMV-mediated m6A methylation of MCU mRNA." (PMID 35359726, 2022).
herpesvirus infection (1 paper, 2025). "Although UL13 homologs are present in all members of the Orthoherpesviridae family, the amino acid sequences of these UL13 homologs show only limited similarity, and it remains to be identified whether the phosphorylation of FTO is a conserved phenotype in (alpha)herpesvirus infection." (PMID 39791911, 2025).
Hypoglycemia (1 paper, 2019). A decreased concentration of glucose in the blood. "Twelve miRNAs that are related to both FOS and FTO were identified and the expression of ten of them was reduced significantly in response to hypoglycemia." (PMID 31728912, 2019). "In the light of these findings and along with the present outcomes, we can confirm the regulatory role of hypothalamic FTO in the mechanisms of hypoglycemia in adult and embryonic neurons within the hypothalamus." (PMID 31728912, 2019). "This interrelationship between the hypothalamic miRNAs and the regulatory protein, FOS and FTO, in response to hypoglycemia facilitates an opportunity to identify potential biomarkers and novel therapeutic targets for HAAF." (PMID 31728912, 2019). "Interestingly, reduced hypothalamic FTO expression was reported in response to hypoglycemia in a dose-dependent fashion." (PMID 31728912, 2019). "It is noteworthy that there was an overlap in the miRNAs between FTO and FOS despite the fact that both had differential responses to hypoglycemia." (PMID 31728912, 2019). "We demonstrated that hypoglycemia modulates the expression of hypothalamic miRNAs that are related to FOS and FTO." (PMID 31728912, 2019). "Taking into account the previous findings, it is crucial to investigate the molecule signature of hypoglycemia and the expression of hypothalamic miRNAs, FOS and FTO simultaneously to propose novel biomarkers for HAAF." (PMID 31728912, 2019).
idiopathic pulmonary fibrosis (1 paper, 2025). Idiopathic pulmonary fibrosis (IPF) is a nonneoplastic pulmonary disease that is characterized by the formation of scar tissue within the lungs in the absence of any known cause. "Additionally, the m6A eraser FTO has been associated with differences in immune cell infiltration and is crucial for the onset, progression, and prognosis of idiopathic pulmonary fibrosis (IPF)." (PMID 39756462, 2025).
infarction (1 paper, 2024). A localised pathological necrosis of tissue resulting from obstruction of the blood supply usually by a thrombus, an embolus, or vascular torsion. "FTO, identified as a cardioprotective factor, suppressed collagen synthesis in post-infarction cardiac fibrosis via m6A modification, which provided a new therapeutic strategy for cardiac fibrosis." (PMID 39538146, 2024).
insulinoma (1 paper, 2020). "Earlier in vitro studies showed that FTO overexpression in MIN6 (mouse insulinoma) cells significantly inhibited insulin secretion in the presence of glucose, but did not affect insulin expression." (PMID 32747736, 2020).
intracerebral hemorrhage (1 paper, 2026). A cerebrovascular disorder characterized by bleeding into one or both cerebral hemispheres including the basal ganglia and the cerebral cortex. "METTL3 mRNA expression was higher in mice with collagenase-induced intracerebral hemorrhage than in controls, whereas WTAP, FTO and ALKBH5 expression was lower in mice with collagenase-induced intracerebral hemorrhage than in controls." (PMID 41601663, 2026).
ischemia reperfusion injury (1 paper, 2025). Adverse functional, metabolic, or structural changes in ischemic tissues resulting from the restoration of blood flow to the tissue (reperfusion), including swelling; hemorrhage; necrosis; and damage from free radicals. "In hepatic ischemia–reperfusion injury (HIRI), FTO expression was reduced, and its overexpression alleviated HIRI by reducing m6A methylated RNA levels, mitigating oxidative stress, and preventing mitochondrial fragmentation both in vivo and in vitro." (PMID 39869517, 2025).
ischemic cardiomyopathy (1 paper, 2024). Ischemic cardiomyopathy is a cardiomyopathy in which a weakness in the muscle of the heart due to inadequate oxygen delivery to the myocardium with coronary artery disease being the most common cause. "The reduction in m6A levels due to FTO overexpression is beneficial to the heart and may improve cardiac dysfunction in ischemic cardiomyopathy, suggesting a potential application of FTO." (PMID 38988324, 2024).